CD151 (CD151 molecule (Raph blood group))
Diseases named in the same sentence as CD151 in open-access papers (continued):
Sharing a sentence is not in itself a finding about the gene and the disease.
cancer (continued). "In particular, several tetraspanins, such as CD151, TSPAN12, and TSPAN8, among others, have been implicated in cancer initiation, progression and metastasis in mammals." (PMID 25978409, 2015). "As a member of the tetraspanin family with four transmembrane domains, CD151 plays a variety of roles in multiple stages of human cancer development and progression." (PMID 25356755, 2014). "Altogether, the literature and the data we report here identify CD151 as an enhancer of de novo tumorigenesis and/or spontaneous metastasis across a broad range of cancer types." (PMID 25012362, 2014). "In cancer cells, CD151 regulates adhesion-dependent signaling and post-adhesion events, including cell migration." (PMID 23717581, 2013). "CD151, identified with one N-glycosylation site, is a cell surface glycoprotein that is known to enhance the motility, invasion and metastasis of cancer cells." (PMID 24324730, 2013). "Overexpression of CD151 was shown to activate integrin and growth factor receptor dependent signaling pathways, which resulted in the increased motility and invasiveness of cancer cells." (PMID 23533596, 2013). "In agreement with poor prognosis of CD151 overexpression in several cancer types, CD151 is a metastasis-promoting tetraspanin protein." (PMID 22294188, 2012). "The positive rate or proportion of CD151 overexpression that is detectable by immunohistochemistry in other cancers is variable." (PMID 22294188, 2012). "A larger prospective study of CD151 in this group of cancers is now being established to confirm these findings." (PMID 21505452, 2011). "In this regard, it is noteworthy that we found a strong correlation in the expression levels of E-cadherin and CD151 in cancer samples." (PMID 21505452, 2011). "Tetraspanin CD151 (also named as SFA-1 and PETA-3), is an important member of the tetraspanin family, and has been widely studied in several malignant tumors." (PMID 21961047, 2011). "CD151 is a small transmembrane protein that regulates cell migration and facilitates cancer metastasis." (PMID 21505452, 2011). "A total of 81 carcinomas (55.5%) were evaluated as CD151-positive and 65 carcinomas (44.5%) as CD151-negative expression." (PMID 12838318, 2003). "Unquestionably, CD151 plays a pivotal role in angiogenesis and cancer metastasis." (PMID 38840183, 2024). "This type of approach is of particular value to delineate key molecular components or interactions in TEM across various cancer types, ultimately accelerating our mechanistic understanding of the crucial role of CD151 and other tetraspanins in tumorigenesis and metastasis." (PMID 33919420, 2021). "Therefore, we infer that CD151 probably affects the sensitivity of NSCLC in response to anti-cancer drugs." (PMID 34108040, 2021). "This study updated our knowledge on CD151 function in cancer progression." (PMID 33767593, 2021). "CD151 is clustered at the cell membrane in specialized multimeric aggregates and can organize distribution and function of interacting laminin-binding integrins and matrix metalloproteinases (MMPs) in cancer cell migration and invasion." (PMID 33015133, 2020). "In this study, the group showed that anti-cancer drug resistance may in part be attributed to CD151 upregulation, for which CD151 knockdown sensitized the cells to drug treatment." (PMID 32117989, 2020). "Basically, while CD44 recruits MMP-9 at the protrusions of migrating cells, thereby spatially directing MMP-9 proteolytic activity, CD151 facilitates MMP-9-mediated cancer cell motility by mediating integrin endocytosis at the rear or basal-lateral front of migrating cells." (PMID 32630531, 2020). "This study showed that whilst CD151 expression was detected on structural or immune cells, these cells also secreted CD151-containing exosomes in circulation to act as components for crosstalk between cancer initiating cells and their environment." (PMID 32117989, 2020).
cancer (continued). "CD151 ablation experiments indicate that CD151 protects cancer cells from anti-cancer drugs." (PMID 30778617, 2019). "Furthermore, CD151-integrin complexes seemed to be involved in protecting cancer cells in the special case of drugs targeting ErbB2." (PMID 30778617, 2019). "CD151 is known to form complexes with integrins and other transmembrane proteins and could be involved in cancer invasion and metastasis." (PMID 29843367, 2018). "Validation of the SDL relationships between RNASEH2A and CD151 in other cancer types is needed." (PMID 29843367, 2018). "High CD151 expression alone has been reported to predict cancer progression in ccRCC patients." (PMID 29843367, 2018). "Altered expression of CD151 was involved in cancer growth, progression, invasion and metastasis." (PMID 29568359, 2018). "Although a number deal of studies have shown that CD151 functions as a promoter gene in various carcinomas, the function of CD151 in RCC and the underlying mechanism has not been studied." (PMID 29568359, 2018). "Enhanced migration of CD151-silenced carcinoma cell sheets was observed in their experiments." (PMID 29568359, 2018). "In that paper, the authors found that CD151 could regulate RhoA activation and the dynamic stability of carcinoma cell-cell contacts." (PMID 29568359, 2018). "High CD151 expression is very likely a general cancer's poor prognostic marker." (PMID 27888619, 2017). "In addition, two other studies have assessed the role of CD151 on de novo tumorigenesis in mouse cancer models other than breast." (PMID 25012362, 2014). "However, there is also evidence that attenuation of CD151 expression impairs α3β1 integrin-dependent cell adhesion and motility over laminin substrates in a number of human carcinoma types." (PMID 25356755, 2014). "Some studies have indicated that CD151 overexpression promotes the metastasis/invasion of cancer cells by mediating integrin signals, while others have argued that an increased expression of CD151 contributes to activate phosphatidylinositol 3-kinase/protein kinase Akt pathway." (PMID 24350713, 2013). "The wide range of functions of CD151, and in particular its involvement in the invasiveness and metastasis of cancer cells, suggest that a better understanding of its expression and role in HGC may be important." (PMID 23533596, 2013). "In 65 cases, CD151 stain was considered to be unsatisfactory because of loss of tissue core or no invasive cancer component, and these cases were further excluded from 951 cases with subtype information." (PMID 22294188, 2012). "Actually, CD151-transfected cancer cell lines enhanced cell migration and invasion." (PMID 22294188, 2012). "CD151 protein was localized to both the membrane and the cytoplasm of cancer cells." (PMID 22272937, 2012). "Moreover, it was reported that the CD151 molecule enhances cell motility, invasion and metastasis of cancer cells and that focal adhesion kinase is needed for these events through CD151." (PMID 12838318, 2003). "In addition, CD151 is a driver of cancer development, progression, and metastasis." (PMID 40464949, 2025). "Furthermore, CD151 is a widely recognized oncogene in a variety of cancers." (PMID 35597804, 2022). "Fourth, anti-cancer drugs failed to induce upregulation of integrin-associated CD151." (PMID 30778617, 2019). "However, in sharp contrast to those previous integrin-dependent results, we here show that nonintegrin-associated CD151 (NIA-CD151) facilitates a more general and previously unreported anti-cancer drug-induced apoptosis." (PMID 30778617, 2019). "However, association of PKCα with CD151 was not altered in cells treated with anti-cancer drugs compared to DMSO." (PMID 30778617, 2019). "Together, these results suggest that the effects of CD151 abrogation on anti-cancer drug-induced apoptosis may be independent of CD151 association with integrins." (PMID 30778617, 2019).
cancer (continued). "Together, these results suggest that upregulated CD151 expression may support not only typical integrin-dependent functions, but also integrin-independent survival of circulating (and possibly metastatic) cancer cells during anti-cancer drug therapy." (PMID 30778617, 2019). "In general, the EV levels of CD9, CD81 and CD151 were increased in OC and B samples compared with Ctrl and PD samples, which could be due to samples being obtained from two different biobanks, but increased levels of EVs have previously been reported in cancer patients." (PMID 40372993, 2025). "Previous research has demonstrated that TSPAN proteins, like CD9, CD81, CD151, and TM4SF1, promote cancer metastasis by interacting with integrin α3β1 or α6, which aligns with our functional enrichment results." (PMID 41347075, 2025). "CD151 also induces MMP9 expression and promotes extracellular matrix degradation and cancer cell migration, which contribute to HCC metastasis." (PMID 39085893, 2024). "Many of these tetraspanins are involved in cancers, chiefly TSPAN1, TSPAN8, TSPAN 13, CD9, CD37, CD63, CD81, CD82 and CD151." (PMID 37046846, 2023). "CD151 can form a complex with integrin α3β1 to activate PI3K or PI4K signaling pathway, and finally impacts cancer cell migration via remodeling actin cytoskeleton or inducing matrix metalloproteinase (MMP) secretion." (PMID 36941633, 2023). "CD151 has been commonly expressed in PRRSV permissive cell lines including MA-104, and MARC-145, as well as in normal and cancer cell lines of human endometrium (RL95-2 and HEC-1-A)." (PMID 37099541, 2023). "Additional markers such as CD151, CD147, and drug transporter proteins (ABCG2/CD338), (MDR1/ABCB1/CD243) have been reported to interact and co-express with CD44 on cancer cells." (PMID 36834918, 2023). "Studies from our group and others have demonstrated that CD151 regulates the ERK and GSK-3β signaling pathways in multiple types of malignant tumors." (PMID 36209197, 2022). "Meanwhile, CD151 can induce MMP9 expression and facilitate extracellular matrix degradation and migration of cancer cells, which all contribute to the metastasis of HCC." (PMID 34540692, 2021). "Based on the available evidence, CD81 and CD82, and TSPAN6 can serve as cancer suppressors, while CD151, TSPAN1, and TSPAN8 act as cancer promoters in the diagnosis and prognosis of HCC patients." (PMID 34540692, 2021). "CD151 can form a complex with integrin α3β1 and regulate PI3K or PI4K signaling pathway in different cancer cells, which finally impacts cancer cell migration via rearrangement of actin cytoskeleton or metalloproteinase secretion." (PMID 34540692, 2021). "The pro- or anti- cancer properties of CD9 is still controversial, while CD151 and TSPAN8 are assumed to display oncogenic activities." (PMID 28423546, 2017). "Among the 33 mammalian members of the Tetraspanins family, at least five of them, CD9, CD37, CD82, CD151 and TSPAN8, are reported to display altered expression in cancers when compared to normal tissues." (PMID 28423546, 2017). "The cell surface expression of other tetraspanin members that play prominent roles in cancer cell invasion including CD63, CD81, and CD151 were unaffected by CD9 overexpression." (PMID 23840773, 2013). "Further comparative studies are needed to resolve differences between the TRA-1-60/CD151/CD166+VE and the α2β1HI CD133+VE cancer stem cell models." (PMID 23145034, 2012). "The factors that predicted poor OS based on the univariate analysis were CD151 overexpression, AJCC stage, cancer subtype, and adjuvant chemotherapy." (PMID 22294188, 2012). "However, it is accepted that the TRA-1-60/CD151/CD166+VE stem cell may have arisen from a cell of origin for cancer that lacks AR, as in our study we did identify a very small fraction (19%) of α2β1HI CD133+VE cells lacking AR expression (0.0002% of the total epithelium)." (PMID 23145034, 2012).
cancer (continued). "We also identified the top 1 GEAR in individual cancer types, such as TLL1 (BLCA), PGK1 (BRCA), RFXANK (CESC), DPP7 (COAD), VWA8 (KIRC), SCMH1 (LGG), HILPDA (LIHC), TLE1 (LUAD), CD151 (LUSC), ANKRD13A (OV), SOCS2 (PAAD), DRG2 (PRAD), ADAMTS6 (STAD), PSMB8 (THCA), ASS1 (UCEC)." (PMID 41404730, 2025). "Targeting CD151 and TSPAN8 in this context may help develop region-specific therapies for inhibiting cancer cell growth in stage 4 primary CC tumors." (PMID 38255741, 2024). "Altogether, TSPAN1, TSPAN15, TSPAN29, and CD151 could support cancer cell growth, while TSPAN31, TSPAN6, CD9, CD37 could inhibit cancer growth." (PMID 36941633, 2023). "However, CD151 has been shown to regulate integrin adhesion activity and extracellular matrix (ECM) remodeling and to be involved in neoangiogenesis and cancer metastasis, including HCC." (PMID 37685904, 2023). "When compared to the cohort of patients without cancer but who had other lung symptomatic diseases, CD151 was significantly upregulated in exosomes from cohorts of AC patients, SCC patients, SCLC patients, and patients with all three subtypes." (PMID 35158999, 2022). "CD151 has carcinogenic effects and has been identified as a negative prognostic indicator in a variety of cancers." (PMID 35597804, 2022). "In squamous cell cancer and SCLC, multimarker models were not superior to CD151 as an individual marker in differentiating cancer patients from non-cancer patients." (PMID 34281588, 2021). "Thus far, DNA hypermethylation in cancer cells has been documented for at least 6 members of the tetraspanin family, including CD9, CD81, CD82, CD151, TSPAN1, TSPAN3, and Uroplakin." (PMID 33919420, 2021). "CD151 is upregulated in human HCC and various other cancers and exerts a positive effect on EMT." (PMID 34540692, 2021). "Therefore, we probed the proteomic data for expression pattern of other well-known cancer stem cell markers such as ALDH1A1 (2.6 fold), CD151 (2.1 fold), CD47 (1.9 fold) and THY1 (3.5 fold)." (PMID 31438645, 2019). "Further evaluation of the 12 gene expression levels in pooled TCGA RNAseq data of different cancer types revealed a strong negative correlation between CD151 and CDK1 expressions (Pearson r = −0.42, p < 0.0001)." (PMID 29843367, 2018). "These striking evidences on the role of CD151 in cancer suggest the tetraspanin would be further considered as a novel potential oncotarget of cancer patients." (PMID 27888619, 2017). "First, as a regulator of laminin-binding integrins, CD151 had been reported to participate in proliferation, epithelial-mesenchymal transition (EMT), migration and invasion of various types of cancer including HCC, suggesting its oncogenic potential in HCC progression." (PMID 27270320, 2016). "CD151 regulates the ligand biding activity of integrin α3β1 and plays a role in Met-dependent signaling and TGF-β signaling, while c-met can regulate many cellular process, especially the proliferation and migration of cancer." (PMID 24330780, 2013). "CD151 also plays a role in the induction of EMT and the overall survival of patients with cancer." (PMID 23717581, 2013). "An emerging consensus is that α6β4 complex synergizes with specific molecules such as ErbB2, EGFR, Ron, Fyn, c-Met, protein kinase C, CD151, and CD9 to activate key signaling pathways for the invasion and migration of carcinoma cells via activation of signaling molecules such as PI3K." (PMID 24015244, 2013). "In B cells and B cell-derived cancers, CD151 expression has not been investigated." (PMID 40464949, 2025). "Notably, none of these pairs have been directly associated with TGFβ signaling or EMT, although many of the identified ligands (e.g., LAMC2) or receptors (e.g., CD151, COL17A1, ITGA2, ITGA3, ITGA6, ITGB1, and ITGB4) occur frequently in the context of EMT and/or cancer." (PMID 36755019, 2023).
cancer (continued). "The expressions of two tetraspanins CD151 and TSPAN8 were found to be significantly elevated in exosomes from cancer patients, which could distinguish cancer from healthy control with AUC of 0.68 and 0.60, respectively, independently of disease stage and histological subtype." (PMID 35757760, 2022). "Whereas in the anti-cancer drug-induced CD151 study, the authors ruled out integrin dependence and proposed that CD151 upregulation may be due to diminished protein degradation." (PMID 32117989, 2020). "However, we show here that CD151 supports anti-cancer drug resistance independent of integrins." (PMID 30778617, 2019). "Hence, CD151’s role in attenuating anti-cancer drug-induced apoptosis may be independent of activation of pro-survival signaling." (PMID 30778617, 2019). "However, the role of CD151 in malignant tumors is not simple." (PMID 21961047, 2011). "The findings indicated that the markers CD151, CD171, and tetraspanin 8 were the most effective in distinguishing patients with cancer, regardless of histological subtype, from those without cancer." (PMID 41573685, 2025). "Of interest, the ability of MMP-9 to favor the spread of tumor cells can also be helped by nonintegrin receptors such as CD44 and CD151, which are coexpressed with MMP-9 by highly invasive cancer cells." (PMID 32630531, 2020). "The markers CD151, CD171, and TSPAN8 were the most effective in differentiating cancer patients of all histological subtypes from those without cancer, with CD151 showing AUC of 0.68 (p = 0.0002), CD171 showing AUC of 0.60 (p = 0.0002) and TSPAN8 showing AUC of 0.60 (p = 0.0002)." (PMID 40575159, 2025). "However, levels of key intermediates of cancer pro-survival pathways (p-mTOR, p-AKT, and p-ERK) were neither diminished when apoptosis was increased (e.g., in CD151-KO cells), nor elevated when apoptosis was reduced (e.g., in CD151 reconstituted cells)." (PMID 30778617, 2019).